MAK (male germ cell associated kinase)
Description:
Essential for the regulation of ciliary length and required for the long-term survival of photoreceptors (By similarity). Phosphorylates FZR1 in a cell cycle-dependent manner. Plays a role in the transcriptional coactivation of AR. Could play an important function in spermatogenesis. May play a role in chromosomal stability in prostate cancer cells.
Synonyms: dJ417M14.2; RP62
Tractability: Small molecule: a high-quality ligand is known; it belongs to a druggable protein family. Antibody: its Gene Ontology location is reachable by antibodies, with high confidence. PROTAC: a small molecule that binds it is known.
Target class: Enzyme; Kinase; CMGC protein kinase group; CMGC protein kinase MAK; Protein Kinase; CMGC protein kinase RCK family
Gene: Protein-coding gene on chromosome 6 (10,762,723 to 10,838,553, reverse strand). Ensembl gene ENSG00000111837.
Subcellular location: Nucleus; Cytoplasm, cytoskeleton, microtubule organizing center, centrosome; Cytoplasm, cytoskeleton, spindle; Midbody; Cell projection, cilium, photoreceptor outer segment; Photoreceptor inner segment
Subcellular location (Human Protein Atlas): Basal body; Connecting piece; Cytosol; Nucleoplasm; End piece; Nucleoli; Plasma membrane; Principal piece
Gene Ontology:
Molecular function: protein binding; protein serine kinase activity; transcription coactivator activity; protein kinase activity; ATP binding; protein serine/threonine kinase activity
Biological process: protein autophosphorylation; protein phosphorylation; cilium assembly; intracellular signal transduction; intraciliary transport; photoreceptor cell maintenance; spermatogenesis; positive regulation of DNA-templated transcription
Cellular component: centrosome; midbody; mitotic spindle; nucleolus; nucleoplasm; nucleus; photoreceptor inner segment; cilium; photoreceptor outer segment; axoneme; motile cilium; photoreceptor connecting cilium; spindle
Genetic constraint (gnomAD): Loss-of-function variants: 46 observed, 65.76 expected, observed/expected ratio (o/e) 0.7, 90% interval 0.55 to 0.89. The upper end of that interval is the gene's LOEUF score, 0.89, which puts it in group 3 of 6, group 1 being the genes least tolerant of losing a copy. Missense variants: 582 observed, 659.63 expected, observed/expected ratio (o/e) 0.88, 90% interval 0.82 to 0.94. Synonymous variants: 209 observed, 239.48 expected, observed/expected ratio (o/e) 0.87, 90% interval 0.78 to 0.98.
Gene-disease validity (ClinGen):
ClinGen rates the evidence that MAK causes each of these diseases.
MAK-related retinopathy (autosomal recessive): Definitive. Any retinopathy caused by variants in the MAK gene.
Homologues: Orthologues: chimpanzee MAK (99% identical), macaque MAK (98% identical), dog MAK (92% identical), pig MAK (86% identical), rabbit MAK (85% identical), rat Mak (84% identical), mouse Mak (83% identical), guinea pig MAK (80% identical), tropical clawed frog mak (63% identical), zebrafish mak (57% identical), Drosophila melanogaster CG42366 (38% identical), Caenorhabditis elegans dyf-5 (37% identical). Paralogues in human: CILK1 (54% identical), MOK (23% identical), MAPK6 (21% identical), MAPK15 (19% identical), MAPK7 (19% identical), MAPK13 (19% identical), MAPK1 (18% identical), MAPK12 (18% identical), MAPK14 (18% identical), MAPK4 (18% identical), MAPK3 (18% identical), MAPK10 (17% identical), and 7 more.
Diseases named in the same sentence as MAK in open-access papers:
MAK is named in the same sentence as 33 diseases in open-access papers, as found by Europe PMC text mining. Sharing a sentence is not in itself a finding about the gene and the disease. The quoted sentences say what the papers report.
retinitis pigmentosa (9 papers, 2013 to 2024). Retinitis pigmentosa (RP) is an inherited retinal dystrophy leading to progressive loss of the photoreceptors and retinal pigment epithelium and resulting in blindness usually after several decades. "Subsequent analyses showed that mutations in the human MAK gene cause the retinal degenerative disease retinitis pigmentosa." (PMID 39293864, 2024). "Some of retinitis pigmentosa patients with the same mutation in the MAK gene represent different severities of disease." (PMID 39293864, 2024). "To gain insight into the effects of heterozygous ICK mutations or variants on the symptoms of retinitis pigmentosa caused by homozygous mutations in the MAK gene in humans, we sought to generate and analyze Mak−/−; Ick+/− mice." (PMID 39293864, 2024). "In humans, MAK variants cause retinitis pigmentosa (RP), in which patients progressively lose their vision." (PMID 38813692, 2024). "Collectively, our results show that the Ccrk-Mak/Ick axis is an IFT regulator essential for retinal photoreceptor maintenance and present activation of Ick as a potential therapeutic approach for retinitis pigmentosa caused by MAK mutations." (PMID 39293864, 2024). "Male germ cell-associated kinase (MAK) is a cilium-associated serine/threonine kinase, and its genetic mutation causes photoreceptor degeneration in mice and retinitis pigmentosa in humans." (PMID 38813692, 2024). "In 2011, distinct classes of MAK mutations were identified as causative mutations in retinitis pigmentosa by two different groups." (PMID 26558903, 2015). "Multiple point mutations in the kinase domain of MAK or an Alu-insertion in exon 9 of MAK have been suggested as potential causes of retinitis pigmentosa, a genetically heritable and autosomal recessive disease." (PMID 24244486, 2013). "In addition, our results shed light on pathological mechanisms underlying retinitis pigmentosa caused by mutations in the human MAK gene and suggest that activation of Ick is a potential therapeutic approach to treat this disease." (PMID 39293864, 2024). "Heterozygous loss-of-function mutations/variants in the human ICK gene may cause more severe symptoms in retinitis pigmentosa patients having MAK mutations." (PMID 39293864, 2024). "For example, our ability to generate photoreceptor cells from patients with molecularly-undiagnosed retinitis pigmentosa allowed us to demonstrate how a newly identified mutation in the gene male germ cell associated kinase (MAK) causes photoreceptor cell-specific disease." (PMID 30959774, 2019). "The patient homozygous for the MAK-Alu insertion (OGI412_881) also had typical retinitis pigmentosa." (PMID 26558903, 2015). "Using this assay in a panel of recessive retinitis pigmentosa probands, they identified the MAK-Alu insertion in 5/240 (2%) probands of mixed ancestry and in 9/35 (26%) probands of Jewish ancestry." (PMID 26558903, 2015). "For example, MAK, negative regulator of cilia length and close relative of ICK and MOK, has been linked to the retina-specific ciliopathy retinitis pigmentosa." (PMID 25243405, 2014). "Non-syndromic retinitis pigmentosa, but not syndromic ciliopathies, exhibited by individuals with MAK gene mutations may be due to genetic interactions between MAK and ICK." (PMID 39293864, 2024).
ciliopathies (6 papers, 2014 to 2025). "Recently, CILK1 and MAK have emerged as potential therapeutic targets for the treatment of ciliopathies and age-related obesity." (PMID 40636449, 2025). "Recently, CILK1 and MAK have emerged as potential therapeutic targets for human diseases including ciliopathies and age-related obesity." (PMID 40636449, 2025). "Although there could be variability in severity, preliminary analyses of the rates of vision loss suggested that EYS is a more rapidly progressive disease than other ciliopathies causing arRP, such as USH2A and MAK." (PMID 28704921, 2017). "Understanding how CILK1 and MAK regulate the IFT turnaround process by phosphorylating the downstream target(s) could reveal the extent to which the activation of CCRK-CILK1/MAK kinase signaling can be more generally applicable to treat human ciliopathies." (PMID 40636449, 2025). "From the data at hand in these three ciliopathies, it can be suggested that EYS peripheral disease progression is faster than that of the MAK and USH2A phenotypes." (PMID 28704921, 2017). "Cumulative evidence of the functional mechanisms of MAK and ICK has unravelled many aspects of the physiological significance of the coordinated IFT turnaround at the ciliary tip and its involvement in human ciliopathies." (PMID 33681987, 2021).
prostate carcinoma (5 papers, 2013 to 2021). A carcinoma that arises from epithelial cells of the prostate gland. "In prostate cancer, overexpression of Male Germ Cell-Associated Kinase (MAK), a male-specific kinase and co-activator of androgen receptor leads to increased expression level of GINS2 by mRNA profiling." (PMID 30413605, 2018). "Therefore, although our data did not reveal any major role for MAK in colon cancer, over-expression of MAK protein could be tightly associated with prostate cancer development." (PMID 24244486, 2013). "MAK is overexpressed in prostate cancer cell lines and clinical specimens and leads to mitosis defects via APC/CCDH1 imbalance." (PMID 34722557, 2021). "MAK plays important role in normal prostate development and prostate cancer progression." (PMID 34722557, 2021). "MAK (Male Germ Cell-Associated Kinase) acts as a coactivator of AR and an androgen-independent intracellular increase of MAK in prostate cancers may mediate androgen independence." (PMID 29562686, 2018). "In vitro studies have shown that prostate cancer cells grown in the presence of high doses of DHT displayed at least two-fold increases in the transcriptional activity of the genes AIB1, CBP, MAK, BRCA1." (PMID 29562686, 2018).
retinal degeneration (5 papers, 2017 to 2024). Degeneration of the retina. "Abnormal ciliary length regulation such as elongation of photoreceptor cilia in male germ cell-associated kinase (Mak) mutant mice is associated with outer segment malformation and retinal degeneration." (PMID 29049287, 2017). "Loss of functional MAK protein, which normally acts as a negative regulator of cilia length, was found to cause elongation of the photoreceptor cell connecting cilia and progressive retinal degeneration in Mak knockout mice." (PMID 34518651, 2022). "In addition, mutations or variants in other genes involved in retrograde IFT may contribute to the severity of retinal degeneration caused by MAK mutations." (PMID 39293864, 2024). "We found that Mak−/−; Ick+/− mice exhibited severe retinal degeneration compared with Mak−/− mice and that MAK and ICK are expressed in photoreceptor cells of the human retina." (PMID 39293864, 2024). "These high confidence variants were found in ABCA4, CERKL, MAK, PEX6 and RDH12 genes associated with retinal degeneration, that could be sufficient to cause pathology." (PMID 39365799, 2024).
brain infarction (2 papers, 2013 to 2015). Tissue necrosis in any area of the brain, including the cerebral hemispheres, the cerebellum, and the brain stem. "In the present study, we demonstrated that 1-week oral pretreatment with MAK exerts moderate but significant protective effects against H/I-induced brain infarction and neurological deficits in type 2 diabetic KKAy mice." (PMID 25945116, 2015). "Orally administered MAK can prevent ischemia–reperfusion-induced oxidative damage to neuronal cells, and reduce the size of cerebral infarcts in animal models." (PMID 24369991, 2013). "Furthermore, we demonstrated that MAK could prevent ischemia–reperfusion-induced oxidative damage and subsequent inflammatory responses in neuronal cells, and reduce the size of cerebral infarcts in animal models." (PMID 24369991, 2013). "Furthermore, MAK prevents MCAO/reperfusion-induced apoptosis and inflammatory responses in neuronal cells and reduces the size of cerebral infarction in STZ-treated rats." (PMID 25945116, 2015).
Anxiety (1 paper, 2013). Intense feelings of nervousness, tension, or panic often arise in response to interpersonal stresses. "In summary, the present study demonstrated that MAK has antidepressant-like potential, which is most likely as a result of the antagonism of 5-HT2A receptors, and possesses anxiolytic-like effects toward memory-dependent and/or stress-induced anxiety in rats." (PMID 24369991, 2013).
autosomal recessive retinitis pigmentosa (1 paper, 2022). Autosomal recessive retinitis pigmentosa (RP) is an autosomally recessive inherited retinal dystrophy leading to progressive loss of the photoreceptors and retinal pigment epithelium and resulting in blindness usually after several decades. "In 2010 we discovered that mutations in the MAK gene were responsible for approximately one third of autosomal recessive retinitis pigmentosa (RP) occurring in individuals of Jewish ancestry." (PMID 34518651, 2022). "By combining next generation whole exome sequencing and induced pluripotent stem cell (iPSC) technology we found that an Alu repeat inserted in exon 9 of the MAK gene results in a loss of normal MAK transcript and development of human autosomal recessive retinitis pigmentosa (RP)." (PMID 34518651, 2022).
breast carcinoma (1 paper, 2021). "In conclusion, we identified and constructed a 5-gene signature (GP6, MAK, DCTN2, TMEM156, and FKBP14) prognostic model to predict prognosis in breast cancer patients." (PMID 34722557, 2021).
colon cancer (1 paper, 2013). "Thus, we analyzed the levels of ICK and MAK proteins in a panel of human primary colon cancer specimens paired with their adjacent normal colonic mucosa tissues." (PMID 24244486, 2013). "A significant increase in the protein level of ICK, but not MAK, was induced in human primary colon cancer specimens." (PMID 24244486, 2013).
Leber congenital amaurosis (1 paper, 2020). Leber congenital amaurosis (LCA) is a retinal dystrophy defined by blindness and responses to electrophysiological stimulation (Ganzfeld electroretinogram (ERG)) below threshold, associated with severe visual impairment within the first year of life. "These genes are known to cause: X-linked RP (RPGR), autosomal recessive RP (MAK and EYS), autosomal dominant RP (PRPF31), Stargardt disease (ABCA4), and Leber congenital amaurosis (GUCY2D)." (PMID 32000842, 2020).
lung adenocarcinoma (1 paper, 2022). A carcinoma that arises from the lung and is characterized by the presence of malignant glandular epithelial cells. "Here, we first report a previously treated advanced lung adenocarcinoma patient with de novo SND1-BRAF fusion who achieves partial response to the MAK inhibitor trametinib." (PMID 36059688, 2022).
prostate tumor (1 paper, 2013). "It is worthy of pointing out that MAK protein is also expressed in prostate epithelial cells and over-expressed in prostate tumor tissues." (PMID 24244486, 2013).
retinal cancer (1 paper, 2010). A malignant neoplasm involving the retina. "Interestingly, ICK or MAK expression is greatly increased in retinal cancer compared to normal retina (SAGE/cDNA Virtual Northern) according to data at the Cancer Genome Anatomy Project)." (PMID 20459822, 2010).
retinal disease (1 paper, 2024). "There were discernible differences in the PCA1 scores between 2 groups; patients with mutations in DHDDS and FAM161A exhibited lower PCA1 scores, indicative of a more severe retinal disease compared to patients with mutations in KIZ and MAK." (PMID 38927740, 2024).
cancer (6 papers, 2010 to 2025). A tumor composed of atypical neoplastic, often pleomorphic cells that invade other tissues. "FLG interacts with MCL1, USP1, C21orf59, MAK, and KIR3DS1 and mucin interacts with ERBB3, SNAI1, TWIST1, TWIST2, and CDH2, all of which, IPA predicted to be associated with cancer." (PMID 31058088, 2019). "Moreover, the enrichment of a higher number of target genes in MAK and PI3/Akt signaling pathways indicates the possible modulation of these pathways and, thereby, the associated cancer hallmarks by WA-induced miRNAs." (PMID 36676955, 2022). "Among these CAF-secreted growth factors, HGF signaling has been shown to be involved in drug resistance through the upregulation of MAK and AKT pathways and in expansion of the cancer stem cell (CSC) population." (PMID 27391808, 2016).
tumor (5 papers, 2013 to 2022). "Indeed, the MAPK/MAK/MRK overlapping kinase (MOK) mRNA was significantly more edited in tumours from patients who relapsed during targeted therapy." (PMID 35993275, 2022). "The results of immunohistochemistry showed that MAK, GP6 and TEMEM156 were significantly highly expressed in tumor tissues, and DCTN2 was highly expressed in normal tissues." (PMID 34722557, 2021).
MAK also shares sentences with these, for which no sentence is quoted: cerebral infarcts (2 papers); diabetes (2); autosomal recessive disease (1); B-cell lymphoma (1); Bardet-Biedl syndrome (1); Bull's eye maculopathy (1); glaucoma (1); ileitis (1); infertile (1); intestinal cancer (1); Joubert syndrome (1); recessive retinitis pigmentosa (1); retinal dystrophies (1); Stargardt disease (1); type 1 diabetes mellitus (1); type 2 diabetes mellitus (1); urticaria (1).